ADAMTS13 (ADAM metallopeptidase with thrombospondin type 1 motif 13)
Diseases named in the same sentence as ADAMTS13 in open-access papers (continued):
Sharing a sentence is not in itself a finding about the gene and the disease.
COVID-19 (continued). "ADAMTS-13 at hospital admission plays a significant role in assessing the risk of death in patients with COVID-19." (PMID 35887770, 2022). "The association between reduced ADAMTS-13 activity and COVID-19 mortality has been proven in multiple studies." (PMID 35887770, 2022). "The reciprocal relationship between VWF and ADAMTS13 in thrombosis is widely studied, and several groups reported that COVID-19 causes a significant increase in formation of large VWF multimers, and decrease in activity and/or levels of ADAMTS13." (PMID 36514048, 2022). "This study shows an imbalance of vonWillebrand /ADAMTS13 axis in pregnant women with COVID-19, leading to a significantly higher and independent risk of preterm delivery." (PMID 35189860, 2022). "In conclusion, the present analysis identifies restoration of the SARS-CoV-2 associated physiological balance of vWf and ADAMTS13 as a new rationale to consider PLEX as a therapeutic option in COVID-19." (PMID 35314740, 2022). "Similar to our study, inverse correlation with von Willebrand cleaving protease, ADAMTS13, and vWF antigen has consistently been associated in both hospitalised and intensive care COVID-19 patients." (PMID 34476137, 2021). "Overall, peak D-dimer levels and the vWF/ADAMTS13 ratio were associated with the severity of critical illness in COVID-19 patients with hypoxic respiratory failure in an ICU setting." (PMID 34476137, 2021). "Several authors reported hemostatic alterations in vWF/ADAMTS13 axis that were strongly associated with disease severity in COVID-19 patients, including increased levels of vWF accompanied by low normal or mildly decreased ADAMTS13 activity." (PMID 34834519, 2021). "Hence, our results neither support nor provide a causal explanation for the genetic mechanisms underlying dysregulated levels of VWF, FVIII or ADAMTS13 in COVID-19 severe patients." (PMID 41585277, 2025). "Studies suggest ADAMTS13 deficiency may also play a role in the long-term complications of COVID-19 or “Long COVID”, which is estimated to affect 30–40% of individuals after infection with SARS-CoV-2." (PMID 39274365, 2024). "The implications of low ADAMTS13 activity in COVID-19 have also been shown in pregnancy, with an increased vWF RiCof:ADAMTS13 activity ratio being significantly associated with a higher risk of pregnancy-related complications including pre-term delivery (OR 1.9, 95% CI 1.1–3.5)." (PMID 39274365, 2024). "Low ADAMTS13 activity and impaired liver function are associated with poor COVID-19 outcomes." (PMID 38608066, 2024). "Since COVID-19 is associated with an increased risk of autoreactivity, the present study investigates, whether the generation of autoantibodies to ADAMTS13 contributes to this finding." (PMID 37380654, 2023). "In an attempt to determine whether genetic polymorphisms in the vWF and ADAMTS13 genes are associated with the progressive severity of COVID-19, χ2-tests were performed by comparing the genotype frequencies of each polymorphism in all patient cohorts." (PMID 36980889, 2023). "Since the presence and concentration of antibodies correlated with severity, the duration of COVID-19 may be a risk factor for development of ADAMTS13 antibodies." (PMID 37380654, 2023). "Markers of endothelial injury such as von Willebrand’s factor (VWF) and its cleaving protein, a disintegrin and metalloproteinase with thrombospondin type 1 motif, member 13 (ADAMTS13), also known as von Willebrand factor-cleaving protease (VWFCP), are also implicated in COVID-19 disease severity." (PMID 37987325, 2023). "In addition, three of nine polyreactive MAbs were strongly cross-reactive against a disintegrin and metalloproteinase with a thrombospondin type 1 motif member 13 (ADAMTS13), an enzyme associated with COVID-19 thrombosis pathology 38,39." (PMID 35927266, 2022).
COVID-19 (continued). "ADAMTS13 gene encodes for a plasma glycoprotein with protease activity that plays a fundamental role in platelet adhesion and aggregation on vascular lesions, and the reduced activity of ADAMTS13 is already reported to be associated with a severe COVID-19 outcome." (PMID 35746657, 2022). "Decreased levels of ADAMTS13 were linked with thrombotic events observed in patients with COVID-19." (PMID 36514048, 2022). "Interestingly, genetic analysis demonstrated that a missense variant of ADAMTS-13 was associated with ICU hospitalization in COVID-19." (PMID 34769508, 2021). "We also show that mild ADAMTS13 activity deficiency is common in COVID-19 inpatients." (PMID 33709050, 2021). "The severe deficiency of ADAMTS13 has also gained attention due to the development of a rare TMA, called immune-mediated thrombotic thrombocytopenic purpura, caused by the production of anti-ADAMTS13 antibodies, in a limited number of subjects after COVID-19 vaccination." (PMID 34834519, 2021). "Additionally, imbalances in von Willebrand factor (VWF) and ADAMTS13, a metalloprotease that cleaves VWF, are implicated in COVID-19-related microangiopathy." (PMID 40850218, 2025). "As both vWF and ADAMTS13 have been shown to play a crucial role in the development of thromboembolism in COVID-19, we aimed to explore whether their missense variants might be correlated with progression scores of the disease by directly modulating the prothrombotic activity of these proteins." (PMID 36980889, 2023). "The low percentage of thrombosis early in the disease is consistent with the hypothesis of gradual depletion of the protease ADAMTS-13 in COVID-19 and its deficiency late in the disease, which leads to an increase in the size and number of VWF multimers underlying thrombus formation." (PMID 35215805, 2022). "Thus, COVID-19 may also represent a form of secondary thrombotic microangiopathy, and mild loss of ADAMTS13 is more likely than is acquired TTP in COVID-19." (PMID 36499042, 2022). "However, a significant alteration in the platelet-vWF-ADAMTS13 axis was found among COVID-19 patients, including high vWF levels with high platelet counts and an increase of 3–7 fold of vWF antigen to ADAMTS13 activity ratio that was strongly associated with COVID-19 severity." (PMID 34372552, 2021). "Therefore, prospective randomized clinical studies are needed to determine the relationship and causality between ADAMTS13 activity, complement, endothelial, and coagulation activation and to study the efficacy of treatments aiming at preventing and/or ameliorating COVID-19 microangiopathy." (PMID 33709050, 2021). "Our findings highlight IL-1α and ADAMTS13 autoantibodies as independent predictors of mortality in severe COVID-19, reflecting the interplay between inflammatory and endothelial pathways." (PMID 41683699, 2026). "•VWF and ADAMTS13 imbalance: One of the most critical aspects of COVID-19-associated microangiopathy is the imbalance between VWF and ADAMTS13, a metalloprotease responsible for cleaving VWF to prevent excessive clot formation." (PMID 40850218, 2025). "Instead, they should be considered exploratory, emphasizing the need for further investigation into the role of low-frequency and rare variation in the VWF and ADAMTS13 genes in critical COVID-19." (PMID 41585277, 2025). "Investigations into coagulation profiles have highlighted a heightened VWF(Ag)/ADAMTS13 ratio, especially in severe COVID-19 cases." (PMID 39941459, 2025). "Research has found that critical COVID-19 patients had a lower ratio of ADAMTS13/VWF activity, suggesting a potential role of both factors in disease progression." (PMID 41585277, 2025). "An imbalance in the von Willebrand factor (vWF)/ADAMTS13 axis and activation of the complement system occur concomitantly in COVID-19 patients and are significantly more pronounced in those with severe disease." (PMID 40508203, 2025).
COVID-19 (continued). "COVID-19-associated TMA was suspected in 17 patients, with 3 cases confirmed as TTP based on ADAMTS-13 activity results." (PMID 40993743, 2025). "Non-coding ABO variants associated with thrombosis, von Willebrand factor levels, and COVID-19 severity reveal topological proximity to ADAMTS13 in endothelial cells." (PMID 41311061, 2025). "Zhang and Bignotti noted significantly elevated plasma levels of VWF in COVID-19 patients compared to healthy controls concomitant with lower plasma ADAMTS13 activity in patients with critical COVID-19." (PMID 40362344, 2025). "The dedicated, prospective design to investigate the role of the vWF/ADAMTS13 axis and complement activation, in order to clarify the issue of COVID-19 coagulopathy as a possible secondary TMA, is the main strength of our study." (PMID 40508203, 2025). "Our findings highlight the simultaneous activation of both the vWF/ADAMTS13 axis and the complement system in severe COVID-19 cases." (PMID 40508203, 2025). "In this retrospective study, we investigated the correlation between BMI and the outcomes of COVID-19 while considering ADAMTS13 activity in 87 hospitalized adult COVID-19 patients." (PMID 38608066, 2024). "When different levels of ADAMTS13 activity were considered, the severity of COVID-19 in obese patients was 4.5 times that in the normal BMI group." (PMID 38608066, 2024). "Recently, the vWF/ADAMTS-13 axis has emerged as a potential therapeutic target for both sepsis and COVID-19." (PMID 38921594, 2024). "When ADAMTS13 activity was considered, obese patients had greater COVID-19 severity and slower viral clearance than those with normal BMI." (PMID 38608066, 2024). "Elevated vWF/ADAMTS-13 ratios have been observed in sepsis and COVID-19 and are positively correlated with high ICU mortality." (PMID 38921594, 2024). "The medical records of 86 COVID-19 patients who were tested for plasma ADAMTS13 activity were reviewed." (PMID 38608066, 2024). "The severity of COVID-19 in obese patients was 4.5-fold that in the comparable group when considering different levels of ADAMTS13 activity (P = .001)." (PMID 38608066, 2024). "We have shown that decreased ADAMTS13 activity is a predictor of poor outcome in COVID-19 patients with kidney damage." (PMID 39457048, 2024). "We investigated the link between body mass index (BMI) and COVID-19 outcomes, using ADAMTS13 activity as a mediator." (PMID 38608066, 2024). "Antiplatelet drugs such as ticlopidine and clopidogrel, interferon, immune checkpoint inhibitors, and COVID-19 vaccines can significantly reduce ADAMTS13 activity after administration, resulting in an inhibitor of ADAMTS13 leading to TTP." (PMID 38732176, 2024). "Further research on the VWF and ADAMTS13 axes in larger cohorts is needed to better understand how obesity interacts with COVID-19 pathogenesis and outcomes." (PMID 38608066, 2024). "Some proposed inhibitors of the ADAMTS13 as the primary mechanism of acquired TTP in COVID-19 patients." (PMID 37350773, 2023). "ADAMTS-13 levels were reduced, with marked inter-individual variation, and the vWf:ADAMTS-13 ratio was increased in convalescent COVID-19 cases, while levels of platelet factor 4 (PF4), a putative protector of vWf, were also elevated in the same population." (PMID 37175942, 2023). "In COVID-19, the ADAMTS13/vWF ratio decreases, leading to an excess of overactive UL-vWF multimers as a key driver of microthromboses in the pulmonary vasculature and SARS-CoV-2-associated ARDS." (PMID 36979908, 2023). "Of note, in this condition, close monitoring of blood routine, ADAMTS13 activity, and anti-ADAMTS13 antibodies following COVID-19 vaccination can contribute to early diagnosis of relapses." (PMID 36836493, 2023). "More importantly, plasma levels of VWF and the ratios of VWF/ADAMTS13 were persistently elevated in patients with COVID-19 throughout hospitalization." (PMID 38002786, 2023).
COVID-19 (continued). "It should be noted that fluctuations in the values of vWF antigen and ADAMTS-13 activity during COVID-19 occur within relatively narrow limits, which reduces the reliability of the forecast." (PMID 38132876, 2023). "COVID-19 patients demonstrate significantly elevated levels of antigen and activity of vWF and mildly to moderately-reduced ADAMTS-13 activity." (PMID 36982387, 2023). "A set of single nucleotide polymorphisms (SNPs) in the vWF (rs216311, rs216321, rs1063856, rs1800378, rs1800383) and ADAMTS13 genes (rs2301612, rs28729234, rs34024143) were genotyped in 72 COVID-19 patients." (PMID 36980889, 2023). "Substantially more critically ill patients with COVID-19 had antibodies to ADAMTS13 compared to non-COVID-19 ICU patients (55.9% vs. 5.6%, OR 21.53, 95% CI 4.609–98.15, p < 0.0001)." (PMID 37380654, 2023). "At baseline, for non-KTRs, differences in several cytokines and vascular mediators were observed when the COVID-19 patients were compared with the HCs, except for ADAMTS-13, myoglobin, IL-9, G-CSF, and TNF-α." (PMID 38005844, 2023). "The absolute reduction in ADAMTS-13 levels in convalescent COVID-19 patients was significantly less marked compared to patients with acute COVID-19." (PMID 37175942, 2023). "After the findings of greatly elevated vWf levels in COVID-19 patients, studies focused on ADAMTS-13, as well as the balance between vWf and ADAMTS-13." (PMID 37175942, 2023). "More patients with COVID-19 already had elevated antibodies to ADAMTS13 at initial sample obtainment compared to healthy controls (22.2% vs. 6.7%, chi squared p=0.0565)." (PMID 37380654, 2023). "Serum vWF levels and ADAMTS13 activity are positively and negatively correlated with COVID-19 severity, respectively." (PMID 36941580, 2023). "Multiple studies have noted a correlation between elevated VWF aggregation (up to five-fold), reduced ADAMTS13 activity, and elevated markers of coagulation in COVID-19 patients." (PMID 37159776, 2023). "In recent literature we found only two small case series with critically ill COVID-19 patients, which detected ADAMTS13 antibodies in only one out of 13 patients." (PMID 37380654, 2023). "Second, both the presence and the concentration of ADAMTS13 antibodies predicted the severity of COVID-19." (PMID 37380654, 2023). "The increase in the vWF/ADAMTS-13 ratio, which reflects the thrombogenicity of the blood, suggests that hypercoagulable state in COVID-19 patients." (PMID 38094124, 2023). "The ADAMTS13/VWF:Ag ratio was substantially lower in COVID-19 patients (20.2±9.4 vs. 82.0±30.7, p<0.0001)." (PMID 37380654, 2023). "Various studies reported that, in severe COVID-19, vWF levels tend to be elevated, accompanied by decreased ADAMTS13 levels." (PMID 38069327, 2023). "The vWF:RCo/ADAMTS-13:activity (Point 1), vWF/ADAMTS-13 (Point 2) and vWF:RCo/ADAMTS-13:activity (Point 2) ratios were significantly higher in patients with moderate and severe COVID-19." (PMID 35887770, 2022). "In conclusion, data from the large multicenter GEN-COVID study allow us to define the prevalence of ADAMTS13 mutations in a SARS-CoV-2-positive population and to establish the severity of COVID-19 pathology in patients carrying the mutation." (PMID 35746657, 2022). "At point 1, ADAMTS-13 activity in moderate and severe COVID-19 was significantly lower than in mild COVID-19." (PMID 35887770, 2022). "We have proven that a decrease in the level and activity of ADAMTS-13 in patients with severe COVID-19 can lead to an imbalance between vWF and ADAMTS-13." (PMID 35887770, 2022). "Plasma ADAMTS13 levels are decreased in patients with severe COVID-19 compared to those with mild disease, and reduced ADAMTS13 levels are associated with increased mortality rates." (PMID 36466841, 2022). "Previously, decreased concentrations of ADAMTS13 were shown to correlate with mortality in COVID-19 and septic shock patients." (PMID 35740360, 2022).
COVID-19 (continued). "Patients with mild and severe COVID-19 symptoms had significantly lower plasma levels of ADAMTS13 than healthy controls." (PMID 36514048, 2022). "In COVID-19 the ADAMTS13/vWf ratio decreases with the severity of the disease and is a strong and independent predictor of mortality." (PMID 35314740, 2022). "In the light of the presented data, it seems promising to further study the role of vWF and ADAMTS-13 in the development of complications of COVID-19 as well as to study their relationship with the long-term outcomes of this disease." (PMID 35887770, 2022). "Since COVID-19 is associated with a significant increase in VWF levels, there is a relative deficiency of ADAMTS-13, resulting in large VWF multimers." (PMID 35215805, 2022). "The elevated vWF and decreased ADAMTS13 levels are the potent predictors of adverse outcomes in severe COVID-19 patients." (PMID 36466841, 2022). "Von Willebrand factor/ADAMTS13 ratio has been found impaired in COVID-19 patients outside pregnancy." (PMID 35189860, 2022). "At point 2, the level of ADAMTS-13 inhibitor was significantly lower in patients with moderate COVID-19." (PMID 35887770, 2022). "A close relationship with the VWF/ADAMTS13 axis and hospitalized COVID-19 (+) patients disease severity (low, intermediate, and high) is identified." (PMID 35087853, 2021). "The most convincing evidence for association with severe COVID-19 was found for five loci: two folate metabolic genes (MTHFR and MTR), two hemostasis inhibitor genes (PROC and ADAMTS13), and a thrombospondin gene (THBS2)." (PMID 34834519, 2021). "The median VWF:AG level, VWF: CBA, and VWF:AG/ADAMTS13 activity ratio were all increased in COVID-19 (+) patients, as compared to the acutely ill COVID-19 (−) cohort." (PMID 35087853, 2021). "The difference in ADAMTS13 activity levels between COVID-19 (+) and COVID-19 (−) patients was minimal, but statistically significant (p = 0.027)." (PMID 35087853, 2021). "We examined the levels of platelets, D-dimers, FVIII, vWF antigen, and ADAMTS13 in critically ill patients with established COVID-19 admitted to ICU." (PMID 34476137, 2021). "The data suggests that increased VWF:AG levels and VWF:CBA in plasmas of COVID-19 (+) patients occurred despite normal ADAMTS13 function." (PMID 35087853, 2021). "These analyses suggest that VWF parameters (i.e., the VWF/ADAMTS13 activity ratio) and thrombin and plasmin generation differed in COVID-19 (+), as compared to COVID-19 (−) patient plasma." (PMID 35087853, 2021). "Given the clinical picture including COVID-19, depressed C3 complement level, acute kidney injury, normal ADAMTS13 level, and response to eculizumab, aHUS triggered by COVID-19 was the most likely diagnosis." (PMID 34903272, 2021). "During the inflammatory activation associated with COVID-19, the vascular imbalance of VWF and ADAMTS13 favors an elevated VWF:AG/ADAMTS13 activity ratio; this shift is implicated in localized endothelial dysfunction of COVID-19 infection." (PMID 35087853, 2021). "On the other hand, significantly elevated VWF:AG, VWF:CBA and VWF:AG/ADAMTS13 activity ratios were observed in COVID-19 (+) patients." (PMID 35087853, 2021). "In our case, we believe that COVID-19, as a viral infection, stimulated anti-ADAMTS13 autoantibodies." (PMID 33648584, 2021). "Consistent with this, several studies documented an association between reduced activity levels of ADAMTS-13 and mortality.We previously found that ADAMTS-13, at hospital admission, predicts mortality in COVID-19 patients." (PMID 34573989, 2021). "VWF:AG, VWF:CBA and VWF:AG/ADAMTS13 activity were significantly increased in COVID-19 (+) patients within the overweight (25–29.9 kg/m2) and obese (>30 kg/m2) BMI groupings." (PMID 35087853, 2021).